PIWIL2 (piwi like RNA-mediated gene silencing 2)
Description:
Endoribonuclease that plays a central role during spermatogenesis by repressing transposable elements and preventing their mobilization, which is essential for the germline integrity (By similarity). Plays an essential role in meiotic differentiation of spermatocytes, germ cell differentiation and in self-renewal of spermatogonial stem cells (By similarity). Acts via the piRNA metabolic process, which mediates the repression of transposable elements during meiosis by forming complexes composed of piRNAs and Piwi proteins and govern the methylation and subsequent repression of transposons (By similarity). During piRNA biosynthesis, plays a key role in the piRNA amplification loop, also named ping-pong amplification cycle, by acting as a 'slicer-competent' piRNA endoribonuclease that cleaves primary piRNAs, which are then loaded onto 'slicer-incompetent' PIWIL4 (By similarity). PIWIL2 slicing produces a pre-miRNA intermediate, which is then processed in mature piRNAs, and as well as a 16 nucleotide by-product that is degraded (By similarity). Required for PIWIL4/MIWI2 nuclear localization and association with secondary piRNAs antisense (By similarity). Besides their function in transposable elements repression, piRNAs are probably involved in other processes during meiosis such as translation regulation (By similarity). Indirectly modulates expression of genes such as PDGFRB, SLC2A1, ITGA6, GJA7, THY1, CD9 and STRA8 (By similarity). When overexpressed, acts as an oncogene by inhibition of apoptosis and promotion of proliferation in tumors. Represses circadian rhythms by promoting the stability and activity of core clock components BMAL1 and CLOCK by inhibiting GSK3B-mediated phosphorylation and ubiquitination-dependent degradation of these proteins.
Synonyms: CT80; HILI; FLJ10351; Mili; PIWIL1L
Tractability: No criterion of Open Targets' tractability assessment is met for any kind of drug.
Gene: Protein-coding gene on chromosome 8 (22,275,316 to 22,357,568, forward strand). Ensembl gene ENSG00000197181.
Subcellular location: Cytoplasm
Pathways (Reactome):
Gene expression (Transcription): PIWI-interacting RNA (piRNA) biogenesis
Gene Ontology:
Molecular function: piRNA binding; protein binding; RNA endonuclease activity; mRNA binding; nucleic acid binding; RNA binding
Biological process: negative regulation of circadian rhythm; germ-line stem cell population maintenance; oogenesis; piRNA processing; positive regulation of cytoplasmic translation; regulatory ncRNA-mediated gene silencing; spermatogenesis; transposable element silencing by heterochromatin formation; transposable element silencing by piRNA-mediated DNA methylation; piRNA-mediated gene silencing by mRNA destabilization; secondary piRNA processing; transposable element silencing by mRNA destabilization
Cellular component: cytoplasm; nucleus; chromatoid body; P granule; PET complex; pi-body; dense body; perinucleolar chromocenter
Genetic constraint (gnomAD): Loss-of-function variants: 28 observed, 47.77 expected, observed/expected ratio (o/e) 0.59, 90% interval 0.43 to 0.8. The upper end of that interval is the gene's LOEUF score, 0.8, which puts it in group 3 of 6, group 1 being the genes least tolerant of losing a copy. Missense variants: 607 observed, 618.34 expected, observed/expected ratio (o/e) 0.98, 90% interval 0.92 to 1.05. Synonymous variants: 235 observed, 230.97 expected, observed/expected ratio (o/e) 1.02, 90% interval 0.91 to 1.13.
Homologues: Orthologues: chimpanzee PIWIL2 (99% identical), macaque PIWIL2 (97% identical), dog PIWIL2 (90% identical), rabbit PIWIL2 (90% identical), rat Piwil2 (89% identical), mouse Piwil2 (88% identical), guinea pig PIWIL2 (86% identical), pig PIWIL2 (86% identical), tropical clawed frog piwil2 (61% identical), zebrafish piwil2 (54% identical), Drosophila melanogaster AGO3 (31% identical). Paralogues in human: PIWIL1 (35% identical), PIWIL4 (32% identical), PIWIL3 (29% identical).
Diseases named in the same sentence as PIWIL2 in open-access papers:
PIWIL2 is named in the same sentence as 89 diseases in open-access papers, as found by Europe PMC text mining. Sharing a sentence is not in itself a finding about the gene and the disease. The quoted sentences say what the papers report.
breast carcinoma (22 papers, 2010 to 2025). "In human breast cancer, Piwil2 overexpression was frequently reported to associate with piRNAs, functioning as an oncogene." (PMID 34295823, 2021). "The PIWIL2 gene is localized in chromosome 8p21.3, and its expression has also been associated with tumor development of some gynecological cancers, renal cell carcinoma, breast cancer, gastric cancer, and colorectal cancer." (PMID 31443431, 2019). "Most of the analyzed cancer types, including colorectal carcinoma, gliomas, gastric cancer, prostate cancer, breast cancer, soft tissue sarcoma, cervical cancer and hepatocellular carcinoma, showed an upregulation of PIWIL2." (PMID 38303021, 2024). "In a cohort of 782 breast cancer patients, PIWIL2 correlated with genes involved in germ cell and stem cell proliferation and differentiation, and regulators of apoptosis belonging to the Bcl family." (PMID 38303021, 2024). "PiRNA-651 recruits DNMT1 to the promoter region of tumor suppressor gene PTEN via PIWIL2, thereby reducing its expression levels and promoting proliferation and invasion of breast cancer cells." (PMID 37325054, 2023). "The complex of piR-932 and PIWIL2 was reported to promote methylation of the promoter region CpG island of the latexin gene, altering latexin expression, and thereby blocking breast cancer metastasis." (PMID 33791297, 2021). "Another study also found that in 334 out of 1086 breast cases, PIWIL2 increased in breast cancer stem cells." (PMID 32211149, 2020). "In particular, the PIWI-like RNA-mediated gene silencing 2 (PIWIL2), a member of the Argonaute family involved in piRNA processing, is significantly overexpressed in both breast cancer stem cells and TGF-β-induced EMT." (PMID 28671581, 2017). "For instance, all PIWI proteins are overexpressed in colon cancer, while only PIWIL2 is expressed in breast cancer." (PMID 26373553, 2015). "TPBG/5T4 expression was used to identify putative lung cancer CSCs while PIWIL2 expression was used to detect putative breast cancer CSCs." (PMID 26496203, 2015). "PIWIL4 has been detected at elevated levels in MDA-MB-231 cells, a breast cancer cell line, and PIWIL2 has been proposed as a promising biomarker for breast cancer, being expressed across various disease stages and present in all examined tissue microarray cores." (PMID 39596284, 2024). "CD44+/CD24−/low CSCs from breast cancer cell lines formed mammospheres and expressed PIWIL2." (PMID 38303021, 2024). "In Piwil2 positive breast cancer stem cells, piR-932 could bind with Piwil2 to suppress the expression of Latexin by promoting methylation of the CpG island at its promoter region." (PMID 34295823, 2021). "In published literature, miR-2276-5p has been reported dysregulated in breast cancer and colorectal cancer, and the researchers used the predictive tools to suggest a relationship between miR-2276 and PIWIL2." (PMID 34141710, 2021). "In view of the negative regulation of cancer stem cells by Latexin, piR-932/Piwil2 could be the potential targets for suppressing the progression of breast cancer." (PMID 34295823, 2021). "For instance, the overexpression of PIWIL2 has been observed in breast cancer." (PMID 32211149, 2020). "Moreover, downregulation of PIWIL2 decreased proliferation and survival of breast cancer stem cells through a decrease in the protein levels of STAT3, BCL-XL and Cyclin D1." (PMID 32357464, 2020). "Also, in PIWIL2 + breast cancer stem cells, due to the methylation of Latexin promotor region (CpG island), Latexin expression levels are significantly lower than normal." (PMID 32211149, 2020). "In a study it was showed that piR-932 /PIWIL2 complex through promoting the methylation of Latex may positively regulate the process of breast cancer stem cells, which in turn promotes EMT (epithelial-mesenchymal transition)." (PMID 30705933, 2019). "It has been suggested that both PIWIL2 and piR-932 could be potential targets for blocking the metastasis of breast cancer." (PMID 30705933, 2019).
breast carcinoma (continued). "In addition, PIWIL2 mRNA levels have been statistically significant lower in breast carcinoma samples compared to normal breast tissues (p < 0.001)." (PMID 31443431, 2019). "For example, PiwiL2 is expressed in precancerous stem cells and breast cancers." (PMID 26861290, 2016). "The PIWIL2 is silenced in adult somatic and stem cells, but is widely expressed in various types of cancers, including hematopoietic, cervical and breast cancers." (PMID 20975993, 2010). "In breast cancer, PIWIL1 and PIWIL3 gene expressions were reported to be upregulated, whereas PIWIL2 and PIWIL4 were downregulated compared with normal breast tissue." (PMID 32987715, 2020). "The primary outcome will be the expression pattern of circulating CSC markers in breast carcinomas including EPCAM, CD44, CD24, ALDH1, CD133, and PIWIL2." (PMID 29258583, 2017). "PIWIL2 was found to be significantly overexpressed in breast cancer stem cells, inducing epithelial-to-mesenchymal transition (EMT) following TGF-β1 treatment, and PIWIL2 also formed a complex with one of three significantly overexpressed piRNAs, piR-932." (PMID 26768585, 2016). "RT-PCR of patients’ tumor samples and breast cancer cell lines were carried out using specific primers for TSGA10, PIWIL2, TEX101 and ODF3 genes." (PMID 23396665, 2012). "Furthermore, transcriptomic analysis of breast cancer revealed consistent downregulation of the PIWI proteins PIWIL2 and PIWIL4, indicating disruption of the piRNA–PIWI pathway in breast cancer." (PMID 41189020, 2025). "Breast cancer cells overexpressing PIWIL2 formed embryonic stem-like colonies in vitro and displayed a lower apoptosis rate compared with PIWIL2-negative cells." (PMID 38303021, 2024). "Furthermore, a stable breast cancer cell line overexpressing PIWIL2 exhibited high POU5F1 and NANOG expression, indicating the embryonic stem-like identity of the PIWIL2-expressing population." (PMID 38303021, 2024). "Half of the breast cancer patients with PIWIL2 expression developed distant metastases within 5 years in contrast with only 13% of the patients without PIWIL2 expression." (PMID 38303021, 2024). "Only 1.67% of breast cancer TMA cores (5/300) and 3% of cervical TMA cores (3/100) were stained by mAb Kao1, in which Piwil2 (Kao1)-expressing cells were usually low in frequency; in contrast, all TMA cores of cervical and breast cancers were stained by mAb Kao2." (PMID 20975993, 2010). "However, PIWIL2 has shown higher expression in nonneoplastic breast tissue than in breast cancer." (PMID 32987715, 2020). "Furthermore, an association with various estrogen-dependent genes such as ANXA1, PIWIL2, CASP4, ESR1/ESR2, PLAC1, and SOCS2, has been shown in breast cancer—however, up to date, no such data concerning adenocarcinomas of the esophagogastric junction have been published." (PMID 31467538, 2019).
colorectal cancer (10 papers, 2019 to 2025). A primary or metastatic malignant neoplasm that affects the colon or rectum. "Functional studies confirm that PIWIL1 and PIWIL2 frequently act as oncogenic drivers in cancers such as glioma, lung, and colorectal carcinoma." (PMID 40725379, 2025). "In colorectal cancer, two independent groups observed the presence of PIWIL2 in most of the analyzed tumor tissues in comparison to weak or no positivity in healthy tissues." (PMID 38303021, 2024). "In this context, aberrant expression of PIWI proteins, especially PIWIL2, has been documented in a wide range of tumors, including colorectal carcinoma, gastric cancer, prostate cancer, breast cancer, gliomas, soft tissue sarcomas, cervical cancer, and hepatocellular carcinoma." (PMID 40725379, 2025). "piRNA has become a diagnostic marker for more and more diseases, for example, piRNA-54265 is up-regulated in colorectal cancer, and could bind with PIWIL2 protein to form a complex to promote the proliferation and metastasis of cancer cells." (PMID 35354120, 2022). "In colorectal cancer (CRC), piR-54265 specifically binds to PIWIL2 and promotes the formation of the PIWIL2/STAT3/phospho-SRC complex and phosphorylation of STAT3, thereby promoting the proliferation and metastasis of CRC cells." (PMID 38915084, 2024). "In colorectal cancer, PIWIL2 has been shown to interact with STAT3 and phospho-SRC leading to STAT3 phosphorylation and an increase in the proliferation, metastasis and chemoresistance of colorectal cancer cells." (PMID 38303021, 2024). "For instance, piRNA-54265 binds with the PIWIL2 protein and promotes the formation of the PIWIL2/STAT3/phosphorylated-SRC (p-SRC) complex, which activates STAT3 signaling and promotes the proliferation, metastasis, and chemo-resistance of colorectal cancer cells." (PMID 33802524, 2021). "For example, piRNA‐54265 can bind to the PIWIL2 protein and promote the formation of the PIWIL2/STAT3/phosphorylated SRC (p‐SRC) complex, activating STAT3 signalling and promoting the proliferation, metastasis and chemotherapy resistance of colorectal cancer cells." (PMID 33942984, 2021). "Furthermore, a positive correlation between PIWIL2 and the undifferentiated cell marker SOX2 have been observed in colorectal cancer tissues." (PMID 31443431, 2019).
cervical cancer (9 papers, 2010 to 2025). A primary or metastatic malignant neoplasm involving the cervix. "PIWIL2 overexpression in cervical cancer initiates metabolic reprogramming via PDK1 upregulation, causing a shift in cellular metabolism from oxidative phosphorylation to glycolysis and the sequential activation of PI3K/AKT/mTOR signaling." (PMID 39849644, 2025). "HPV16 is also able to increase PIWIL2 levels to increase proliferation and invasion of cervical cancer cells." (PMID 32357464, 2020). "In primary breast and cervical cancers, full length PIWIL2 proteins were detected mainly in apoptotic tumor cells but little in the living tumor cells, when monoclonal antibody (mAb) to PIWIL2 was used." (PMID 28545024, 2017). "To explore the histological patterns of Piwil2 expression throughout cervical cancer development, we first measured Piwil2 expression by immunohistochemistry (IHC) analysis in formalin-fixed paraffin-embedded samples derived from cervical lesions." (PMID 27602489, 2016). "In this work, we sought to expand knowledge of Piwil2 expression during cervical cancer tumorigenesis." (PMID 27602489, 2016). "Because Piwil2 promotes proliferation and inhibits apoptosis in tumor cells, it is rational to exploit the tumor-suppressing effects of cervical cancer therapeutic approaches." (PMID 27602489, 2016). "Together, these results demonstrate that the knockdown of Piwil2 confers anti-tumor effects in vitro and in vivo in cervical cancer." (PMID 27602489, 2016). "Previous studies from our group and others have demonstrated that Piwil2 is expressed in cervical CSCs from cervical cancer patients as well as in cervical cancer cell lines." (PMID 27602489, 2016). "While PL2L proteins can be widely detected in the euchromatin-enriched proliferating tumor cells in primary and metastatic cancers, such as breast and cervical cancers, PIWIL2 was detected mainly in apoptotic or apoptosing cells." (PMID 20975993, 2010). "Similarly, knockdown of PIWIL2 in cervical cancer cells led to a marked reduction in proliferation and colony formation, in vivo tumorigenicity, chemoresistance, and the proportion of cancer stem-like cells." (PMID 39849644, 2025). "PIWIL2 downregulation in cervical cancer cells resulted in reduced proliferation and invasion." (PMID 38303021, 2024). "Overall, it shows the importance of the role PIWIL2 plays in the carcinogenesis of cervical cancer." (PMID 39596284, 2024). "Notably, when Piwil2 was knocked down, the proliferation and invasion of cervical cancer cell lines were significantly inhibited." (PMID 27602489, 2016). "However, the expression of PIWIL2 has been observed in various types of primary cancers and tumor cell lines, including breast cancer, cervical cancer, gastric cancer,acute myeloid leukemia, colorectal cancer, colon cancer, ovarian cancer and testicular germ cell tumors, etc." (PMID 28545024, 2017). "Therefore, targeting Piwil2 may be an effective therapeutic option for patients with cervical cancer and CIN lesions in particular." (PMID 27602489, 2016). "Moreover, in cervical cancer cells, Piwil2 overexpression also induced a significant upregulation of c-Myc, Nanog, Oct4, Sox2, and Klf4, increased the proportion of cells that were ALDH, MSCA-1, and ABCG2 positive and subsequently increased cisplatin resistance." (PMID 27602489, 2016). "There has been a significant body of statistics collected on the presence of PIWIL2 protein and its mRNA transcript in various types of cancers including breast tumors, acute myeloid leukemia, papillary thyroid carcinoma, as well as colorectal, colon, gastric, ovarian and cervical cancers." (PMID 25384072, 2014).
cervical cancer (continued). "Here, we observed that the germ stem cell protein Piwil2 is expressed in pre-cancerous and malignant lesions of the cervix and cervical cancer cell lines with the exception of the non-HPV-infected C33a cell line." (PMID 27602489, 2016). "In HeLa, SiHa, and CaSki cervical cancer cell lines, which contain an integrated HR-HPV genome of type 18, 16, or both, respectively, Piwil2 expression was observed; however, in the C33a cell line, which is negative for HR-HPV DNA and RNA, no expression was detectable." (PMID 27602489, 2016). "Because Piwil2 is expressed in the pre-cancer stage of CIN2/3 and maintains the oncogenicity of cervical cancer cells, we sought to investigate whether Piwil2 plays an essential role in somatic cell malignant transformation." (PMID 27602489, 2016). "Then, we used the mAbs Kao1 and Kao2/3 (thereafter referred to as Kao2) to examine the expression of Piwil2 and PL2L proteins in the tissue microarray (TMA) cores of human breast (n = 300) and cervical cancers (n = 100) or in some tissues sections of the cancers." (PMID 20975993, 2010). "In cervical cancer cells, HPV16 infection might increase the expression of PIWIL2." (PMID 39596284, 2024). "Consistently, PL2L proteins rather than Piwil2 are predominantly expressed in the cytoplasm or cytoplasm and nucleus of euchromatin-enriched tumor cells in human primary and metastatic cancers, such as breast and cervical cancers." (PMID 20975993, 2010). "No Piwil2 expression was observed in the basal layer of the normal cervix epithelium, whereas lesion cells in CIN2/3 and cervical cancer exhibited positive cytoplasmic and nuclear staining." (PMID 27602489, 2016).